CCL2 (C-C motif chemokine ligand 2)
Diseases named in the same sentence as CCL2 in open-access papers (continued):
Sharing a sentence is not in itself a finding about the gene and the disease.
malaria (continued). "The results indicate that differential expression of CXCL10, TNF-α, CCL2, IL-8, and IL-6 were tightly linked to hemoglobin genotype and severity of Plasmodium infection and that these cytokine levels may be predictive for susceptibility to severe malaria or SCD severity." (PMID 33424841, 2020). "Co‐incubation of macrophages with XO and iRBCL also induced synergistic production of the chemokines IL‐8, CCL5, and CCL2, which are essential in the recruitment and activation of leukocytes to sites of inflammation and are also elevated during malaria." (PMID 31265218, 2019). "The group of malaria mono-infected patients exhibited a biosignature composed by higher levels of IL-10 and CCL2 whereas the group of dengue mono-infected individuals displayed a signature with high expression of IL-4, IL-7 and Il-12 in plasma." (PMID 26271921, 2015). "Regarding malaria mono-infection, IL-10 and CCL2 were the immune markers with more relevant elevations in plasma." (PMID 26271921, 2015). "Additionally, mice lacking CCR2 were completely susceptible to cerebral malaria, highlighting the importance of MCP-1/CCL-2 in malaria pathophysiology." (PMID 39567619, 2024). "MCP-1/CCL-2 was reported to be related to monocyte infiltration into the intervillous space of malaria-infected placentas, suggesting that high MCP-1/CCL-2 expression may act as an early signal for monocyte recruitment." (PMID 39567619, 2024). "The observed differences in MCP-1/CCL-2 levels between malaria-infected and uninfected patients may also be influenced by the specific Plasmodium species involved." (PMID 39567619, 2024). "Although MCP-1/CCL-2 is associated with severe malaria, a previous study demonstrated that MCP-1/CCL-2 is also linked to uncomplicated malaria, as asymptomatic malarial infection in co-infected patients exhibited higher MCP-1/CCL-2 levels than symptomatic P. vivax infections." (PMID 39567619, 2024). "When stratifying by P falciparum infection, elevated BAFF and downregulated CCL2 and IL‐10 were independently associated with nodding syndrome in children who were malaria‐positive and malaria‐negative." (PMID 34033255, 2021). "This may indicate in HbAC individuals CCL2 plays a role in their protective mechanism against malaria." (PMID 33424841, 2020). "In addition, AST seemed to be highly influenced by immune molecules in the malaria and dengue co-infected patients as this enzyme was positively correlated with CCL2, IL-13 and IL-8." (PMID 26271921, 2015). "However, there was a significant increase in MCP-1/CCL-2 levels in patients with severe malaria." (PMID 39567619, 2024). "Therefore, these confluent events from responses to both pathogens (increased production of IL-10, CCL2 protective role in malaria, as well as combined effects of IL-4 and IL-10) could enable the host to respond properly without unbalanced inflammation." (PMID 31233500, 2019). "In malaria patients with HbS, serum levels of C-X-C motif chemokine ligand 10 (CXCL10), tumor necrosis factor-α (TNF-α), chemokine (C-C motif) ligand 2 (CCL2), interleukin-8 (IL-8), and interleukin-6 (IL-6) are lower compare to malaria patients without HbS." (PMID 40993672, 2025). "The objective of this study was to synthesize evidence on variations in MCP-1/CCL-2 levels in relation to Plasmodium infections and malaria severity." (PMID 39567619, 2024). "Increased TNF, IFN-γ, IL-1, IL-2, IL-6, IL-10, TGF-β, CCL2, CCL3, and G-CSF levels and decreased IL-5, IL-12, IL-17, and CCL11 levels were observed in malaria monoinfection compared to intestinal parasite monoinfection." (PMID 36716305, 2023). "For intestinal parasite infections, increased TNF, IL-1, IL-6, IL-10, CCL2 and decreased IL-4, IL-17, TGF-β were observed in malaria coinfections compared to intestinal parasite monoinfection." (PMID 36716305, 2023). "Increased TNF, IFN-γ, IL-6, IL-10, IL-17, CCL2, and CCL3 levels and decreased IL-7 levels were observed in malaria monoinfection compared to dengue virus monoinfection." (PMID 36716305, 2023).
malaria (continued). "Distinct cytokine profiles in malaria and HBV coinfections were TNF, IFN-γ, IL-4, IL-6, IL-10, IL-12, and CCL2." (PMID 36716305, 2023). "Patients with malaria-HBV coinfection presented elevated concentrations of multiple variables such as IFN-γ, TNF-α, IL-4, IL-10, CCL2, and reduced levels of IL-12 and creatinine levels when compared to those with asymptomatic vivax malaria monoinfection." (PMID 31233500, 2019). "In another study, IL-8/CXCL8 was elevated in CSF of non-fatal CM cases of P. falciparum-infected children, while MCP-1/CCL2, MIP-1α/CCL3, MIP-1β/CCL4, and RANTES/CCL5 levels were comparable to malaria-free controls." (PMID 28775960, 2017). "In this malaria model, IFN-γ signalling and concurrent secretion of C-C motif ligand 2/7 (CCL2/CCL7) chemokines by BM stromal cells seem required for HSPC mobilization." (PMID 26903708, 2016). "Plasma levels of inflammatory cytokines (IFNα, IFNγ, TNF, IL-6) and chemokines (CCL2, CCL3, CCL4, CXCL10) were significantly higher during severe malaria compared to convalescence." (PMID 27792766, 2016). "In malaria, both CXCL10 and CCL2 serum protein levels increased reaching peak levels between day 4 and 7 after infection whereas CCL7 was constitutively deregulated in Ccr2-deficient animals." (PMID 23762028, 2013). "The systemic presence of CCL2 and CCL7 in malaria, mainly at early time points in infection, was critically dependent on intact IFN-γ signaling and not affected by the absence of TLR-signalling." (PMID 23762028, 2013). "Chemokine release is also associated with the malaria blood stage, but HZ alone did not induce the secretion of any of the chemokines investigated, CXCL8 (IL-8), CXCL9, CXCL10, CCL2 and CCL5." (PMID 40717771, 2025). "The meta-analysis revealed significantly higher MCP-1/CCL-2 levels in participants with severe Plasmodium infections compared to those with non-severe malaria (P: 0.04, SMD: 1.51, 95% CI: 0.06–2.95, I2: 98.5%, number of participants: 1371)." (PMID 39567619, 2024). "Results revealed significantly higher MCP-1/CCL-2 levels in participants with severe Plasmodium infections compared to those with non-severe malaria (P: 0.04, SMD: 1.51, 95% CI: 0.06–2.95, I2: 98.5%, number of participants: 1371)." (PMID 39567619, 2024). "CCL2 is involved in the immune response to HIV, TB, malaria, and COVID‐19." (PMID 38099246, 2023). "Global analysis of lung tissues and BALF of infected mice with MA-ARDS revealed elevated levels of the cytokines and chemokines also reported in the serum of severe malaria in humans mainly, IL-1, IL-6, IL-8, IL-10, TNF-α, IFN-γ, MCP-1/CCL2, MIP-2/CXCL2, IP-10/CXCL10, KC/CXCL1, VEGF, PIGF." (PMID 35677654, 2022). "In this study, we identified genes related to the malaria resistance pathway (KEGG: hsa05144), including CCL2, CD40, HBA1, and HBA2 as the differential genes in DAI, indicating different selective pressure posed by malaria on the DAI compared to other M.Yunnan.West." (PMID 35864541, 2022). "Despite that, in participants with symptomatic malaria, the degree of CCL2 perturbation exhibited two negative correlations, vs. IL-6 and TNF-α." (PMID 34727121, 2021). "mDCs from malaria-exposed adults also secreted the Th1-associated chemokines CXCL9 (MIG) and CXCL10 (IP-10) as well as CCL2 but no CCL5." (PMID 33407502, 2021). "Inflammatory chemokines CXCL10, CCL2, and CCL3 as well as cytokines, TNF-α, IL-8, and IL-6 were differentially expressed in individuals with different hemoglobin genotypes that were infected or uninfected with malaria parasites." (PMID 33424841, 2020). "Severe malaria patients exhibit high levels of serum pro-inflammatory cytokines (TNF, IL-1β, IL-6, IL-8, IL-12, IFNγ) and chemokines (CCL2, CCL5, CXCL9, CXCL10), and lower levels of regulatory cytokines (IL-10, TGFβ, PGE2) compared to those with mild and asymptomatic malaria." (PMID 27792766, 2016).
malaria (continued). "In the group of patients with malaria and dengue co-infection, HB and HT displayed negative associations with IL-7, whereas AST exhibited positive interactions with CCL2, IL-13 and IL-8." (PMID 26271921, 2015). "The results show that in early malaria, selected immune response-related genes were up-regulated including α β and γ interferon-related genes, as well as genes of IL-15, CD36, chemokines (CXCL10, CCL2, S100A8/9, CXCL9, and CXCL11), TRAIL and IgG Fc receptors." (PMID 24188121, 2013). "However, for the malaria group, four distinct correlation patterns were observed; first pattern (CCL4, CCL2, CCL3, IL12 and IL2), second pattern (IL-17A, IL-1β, CCL11, IL4), third pattern (IL5, IL7, IL13), and fourth pattern (IL1RA, CXCL10, TNFα, IL2R, CXCL9, IL6)." (PMID 35811678, 2022). "We evaluated the expression of CXCL10, TNF-α, CCL2, CCL3, IL-8, and IL-6 among 74 volunteers, from a pool of 923, with one (HbAS and HbAC), two (HbSS, HbSC, HbCC) and no (HbAA) copies of the Hb allele variant S and/or C with (+) and without (-) malaria." (PMID 33424841, 2020). "In addition to producing type I IFNs, DCs produce a wide range of pro-inflammatory cytokines, including TNF-α, IL-12, and IL-6, and chemokines, such as CXCL1, CXCL2, CCL2, CCL5, CXCL9, and CXCL10 in response to malaria parasites, and play crucial roles in malaria immunity and pathogenesis." (PMID 30619355, 2018). "We report high plasma levels of proinflammatory cytokines and chemokines (IFNγ, TNF, IL-6, CCL2, CCL3, CCL4, CXCL10) in severe malaria patients compared to baseline uninfected follow-up, which matched that of Py infection in mice in which we could conduct a temporal analysis." (PMID 27792766, 2016). "Placentas from malaria-infected litters (wild-type and C5ar-/-) showed placental inflammation as indicated by increased expression of tumor necrosis factor (TNF), interferon gamma (IFNΥ), intracellular adhesion molecule-1 (ICAM-1) and monocyte chemotactic protein 1 (MCP-1, CCL2) (p < 0.05)." (PMID 26402732, 2015). "In the group of individuals presenting with severe non-lethal malaria, parasitaemia displayed significant positive associations with TNF, sTNF-RI, IFN-γ, IL-10, CXCL9, CXCL10, SOD-1 and HO-1, while negatively correlated with the chemokines IL-8 and CCL2." (PMID 23433077, 2013). "However, while these findings provide valuable insights, it is important to note that preclinical studies may not fully translate to human malaria, and further research is needed to clarify MCP-1/CCL-2’s role in human infection." (PMID 39567619, 2024). "Pro-inflammatory chemokines (CXCL10, CCL2, and CCL3) and cytokines (TNF-α, IL-8, and IL-6) were reported to mediate severe malaria and SCD separately but have not been examined in SCD individuals infected with malaria." (PMID 33424841, 2020). "Chemotaxis to CCL2 and expression of CCR2 by neutrophils were minimal and not altered in malaria patients." (PMID 22745844, 2012). "However, the overall meta-analysis suggested no significant alteration in MCP-1/CCL-2 levels in Plasmodium-infected individuals, suggesting that the role of MCP-1/CCL-2 in malaria pathophysiology is complex." (PMID 39567619, 2024). "The subgroup meta-analysis of MCP-1/CCL-2 levels between participants with severe Plasmodium infections and those with non-severe malaria reveals substantial variability influenced by publication years, continents, and types of blood samples used for measuring MCP-1/CCL-2 levels." (PMID 39567619, 2024).
autoimmune disease (63 papers, 2007 to 2025). A disorder resulting from loss of function or tissue destruction of an organ or multiple organs, arising from humoral or cellular immune responses of the individual to their own tissue constituents. "These pathways lead to the transcription of pro-inflammatory cytokines, such as TNF-α, as well as chemokines such as CCL2 (MCP-1), implicated in the development of many autoimmune diseases, including SLE." (PMID 26617609, 2015). "CCL2 plays a crucial role as a chemokine in the pathogenesis of numerous inflammatory and autoimmune diseases." (PMID 39403387, 2024). "In an autoimmune disease model, CCL2 expression results in accumulation of myeloid dendritic cells in the central nervous system." (PMID 38057698, 2023). "Conclusively, targeting the CCL2/CCR2 axis is considered to be an attractive target for the treatment of autoimmune diseases and viral infections." (PMID 35702353, 2022). "Monocyte chemoattractant protein-1 (MCP-1, CCL2) is expressed in inflammatory conditions, is a chemoattractant for monocytes and T lymphocytes, and plays a pivotal role in autoimmune diseases." (PMID 18001476, 2007). "It has been reported that in autoimmune diseases, the formation of an inflammatory microenvironment induces the production of CCL2 in response to inflammatory cytokines such as IL‐1β, which recruits and expands macrophage aggregation at the site of inflammation." (PMID 40500868, 2025). "CCL2 may represent a potential intervention target for the treatment of various diseases, including autoimmune diseases." (PMID 38255988, 2024). "CCL2 is considered as a potential target for the treatment of several autoimmune diseases." (PMID 38255988, 2024). "CCL2, as a pro-inflammatory cytokine, is secreted by the tumor, endothelial, fibroblasts, epithelial, smooth muscle, mesangial, astrocytic, monocytic, and microglial cells and participates in the pathogenesis of various cancers and autoimmune diseases." (PMID 36357631, 2023). "The relationship between the CCL2/CCR2 signaling axis and the pathogenesis of autoimmune diseases has also been widely investigated, and a common pathological feature of these autoimmune diseases is the upregulation of CCL2 and/or CCR2 expression in the lesions." (PMID 35702353, 2022). "CCL2 belongs to the C-C chemokines group and has been identified as an inflammatory modulator, which regulates macrophage recruitment during infection, the healing process, and autoimmune diseases." (PMID 31665136, 2019). "Moreover, the importance of the CCL2/CCR2 axis in recruiting inflammatory monocytes to sites that may activate a regulatory phenotype in these cells indicates the importance of polymorphisms in this axis that could impact on susceptibility to autoimmune disease." (PMID 22912822, 2012). "In the brain, the chemokine ligand 2 (CCL2 or monocyte chemotactic protein-1) and its receptors chemokine receptor 2 (CCR2) and chemokine receptor 4 (CCR4) have been implicated in a number of neuropathologies ranging from traumatic brain injury to autoimmune diseases." (PMID 25012628, 2014). "In autoimmune diseases such as SLE, increased expression of chemokine receptors (CXCR2, CXCR3, CCR3 and CCR1) and elevated levels of chemokines such as MCP-1/CCL2, MIP-1/CCL-4, SDF-1/CXCL-12, RANTES/CCL5 and IP-10/CXCL-10 are observed." (PMID 36059466, 2022). "CCL2 and CXCL10 are classic chemokines that can chemoattract lymphocytes and monocyte macrophages to infiltrate target organs, which are involved in the initiation of immune response and acceleration of the inflammation development and are related to many autoimmune diseases, including HT." (PMID 36874364, 2023).
Cerebral ischemia (63 papers, 2007 to 2025). Restriction of arterial blood supply to the brain associated with insufficient oxygenation to support the metabolic requirements of the tissue. "Our findings suggested that ATF3 repressed neuronal apoptosis and microglia activation caused by cerebral ischemia via targeting CCL2 and mediating the TLR4/NF‐κB signaling." (PMID 35263513, 2022). "Among the chemokines implicated in cerebral ischemia, MCP-1 (also known as CCL2) and MIP-1α have been shown to play an important role in promoting tissue damage via recruitment of inflammatory cells." (PMID 25972779, 2015). "In conclusion, CCL2 and CCR2 are involved in the pathogenic mechanisms underlying cerebral ischemia/reperfusion injury in rats, and preadministration of propofol can suppress the expression of CCL2 and CCR2." (PMID 25009636, 2014). "Therefore, CCL2 and CCR2 may be involved in the mechanisms underlying cerebral ischemia/reperfusion injury, and propofol may protect the brain through regulating the expression of CCL2 and CCR2." (PMID 25009636, 2014). "Postmortem studies on animals and humans have demonstrated that cerebral ischemia initiates the expression of various chemokine classes in the brain, such as CCL2, CCL3, CCL5, CXCL8, CXCL10, and CXCL12." (PMID 38861234, 2025). "The chemokine (C-C motif) ligand 2/chemokine receptor 2 (CCL2/CCR2) signaling pathway is implicated in acute neuroinflammation and BBB dysfunction following cerebral ischemia-reperfusion." (PMID 40766753, 2025). "Inhibition of CXCL5, CXCL13, XCL-1,and CCL2/MCP-1 during the cerebral ischemia/reperfusion (CI/R) phase of VaD holds promise as a therapeutic strategy to mitigate microglial activation and minimize neurological injury." (PMID 39206161, 2024). "The genes CCL2, ICAM1, and JUN were identified as being associated with neurological disorders such as brain ischemia and schizophrenia." (PMID 39024368, 2024). "Administration of anti-CD147 inhibited inflammatory cytokine (TNFα, IL-6, IL-1β) and monocyte chemotactic protein-1 (MCP-1, CCL2) expression in the spleen, and this was associated with reduced brain injury in cerebral ischemia." (PMID 36119117, 2022). "This demonstrates the high expression of CCL2 in neurons earlier than that in astrocytes, indicating the special significance of CCL2 in neuronal injury or neuroprotection induced by cerebral ischemia-reperfusion." (PMID 35408846, 2022). "In the acute phase of cerebral ischemia-reperfusion, the expression of CCL2/CCR2 is increased in the ischemic penumbra, which promotes neuroinflammation and enhances brain injury." (PMID 35408846, 2022). "The results demonstrated that ATF3 protein was significantly reduced and CCL2 protein was significantly increased in rats with cerebral ischemia, while TLR4/NF‐κB signaling pathway was significantly activated in MCAO rats." (PMID 35263513, 2022). "In the ischemic area induced by cerebral ischemia-reperfusion, the expression of CCL2 is time- and cell-specific." (PMID 35408846, 2022). "To evaluate the degree of angiogenesis after transplantation of CCL2-overexpressing hUC-MSCs following brain ischemia, we immunostained for VEGF and RECA-1 to evaluate angiogenesis and microvessel density in the peri-infarct area, respectively." (PMID 33096826, 2020). "CCL2 is expressed by neurons throughout the brain and its expression level in glial cells is increased in epilepsy, brain ischemia, AD, experimental autoimmune encephalomyelitis (EAE), and traumatic brain injury (TBI)." (PMID 25635231, 2014). "The highest expression of CCL2 was observed in our model at 24 h after initiation of brain ischemia." (PMID 24324296, 2013). "In addition, we identified and verified HGF, TGF-α, and CCL2 as dysregulated proteins in the lungs after cerebral ischemia." (PMID 35897671, 2022).